CAMP (cathelicidin antimicrobial peptide)
Diseases named in the same sentence as CAMP in open-access papers (continued):
Sharing a sentence is not in itself a finding about the gene and the disease.
cancer (65 papers, 2009 to 2026). A tumor composed of atypical neoplastic, often pleomorphic cells that invade other tissues. "The authors synthesized the trimeric prodrug system in which three molecules of the anti-cancer drug CAMP (pro-CAMP) were linked through a retro-aldol, retro-Michael trigger to a substrate for the catalytic antibody 38C2." (PMID 38794329, 2024). "Notably, we detected several critical regulating proteins associated with cancer processes, such as CAMP, MMP9, the S100 family (100A8, S100A9, S100A12), and PRTN3, among the proteins with the most significant increases." (PMID 37231509, 2023). "Furthermore, pathway enrichment analysis revealed that the genes regulated by eRNAs were implicated in canonical cancer pathways, including endocytosis, axon guidance, and cathelicidin antimicrobial peptide (cAMP), indicating a tendency toward oncogene regulation." (PMID 38863031, 2024). "CAMP gene (encoding pre-hCAP18) is an important primary vitamin D target gene in the VDR pathway, and hCAP18/LL-37 is induced by 1,25(OH)2D3 in several cell types, including various immune, epithelial, and some cancer cell." (PMID 35039485, 2022). "More importantly, a cell-specific methylation pattern in the promoter region of human CAMP was detected, which suggests that LL-37 plays a suppressive role in the progression of this cancer." (PMID 35625823, 2022). "Taken together, LTF, ARG1, PGLYRP1, S100A12 and CAMP/LL-37 affect the human immune system at various levels by producing both protumorigenic and anticancer effects in a tissue- and cancer-specific manner." (PMID 36230605, 2022). "Our finding that the antimicrobial CAMP peptide kills cancer cells is consistent with previous reports and suggests that adding CAMP is a potential way to counteract the pro-cancer effect of ATF3, thus improving chemotherapy." (PMID 34298975, 2021). "The result showed that the expression of CAMP was upregulated significantly in the cancer tissues compared to the normal tissues." (PMID 32365569, 2020). "Further, they created a modification of the Cathelicidin antimicrobial peptide (CAMP/CAP18), called sCAP18, that enhances cancer cell EV uptake by inducing macropinocytosis." (PMID 39698114, 2020). "CAMP was overexpressed in lung, breast, ovarian, prostate, pancreatic cancer, melanoma, and skin squamous cell carcinoma and facilitated cancer cell growth." (PMID 32365569, 2020). "CAMP was reported to exert its cancer-related roles by regulating cell proliferation, invasion, migration, apoptosis, and cell cycle." (PMID 32365569, 2020). "Taken together, CAMP was regarded as a target mediator in the cell–cell interaction between TAMs and cancer cells." (PMID 32365569, 2020). "Additionally, the expression of the CAMP gene in various cancer cells is inducible, for instance, by vitamin D3." (PMID 39339270, 2024). "In our study, CAMP was upregulated in both cancer tissues and circulation." (PMID 32365569, 2020). "Similarly, we also observed a significant inhibition of ALDH activity, which is a well-known cancer stem cell marker, upon CAMP knockdown, which provides evidence that CAMP is stemness-related." (PMID 32365569, 2020). "The results also suggested that the hypermethylation of CpG sites at CAMP-F2 in human CAMP promoter may participate into the inhibitory effects on the expression of human CAMP in these epithelial cancer cells." (PMID 28427192, 2017). "Based on these results, we speculated that DNA methylation of these CpG sites in the promoter region might play important roles during carcinogenesis via directly downregulating human CAMP promoter activity in cancer progression for OSCC." (PMID 28427192, 2017). "Paradoxical effects have been described for cathelicidin (CAMP) in cancer biology." (PMID 27832772, 2016). "Low expression of the CAMP gene could serve as an important biomarker for these cancers." (PMID 39339270, 2024).
cancer (continued). "Therefore, there may be a strong association between human cathelicidin antimicrobial peptide LL-37, inflammation, and cancer development, and LL-37 may have unexpected positive effects for several types of cancer in normal conditions." (PMID 26175965, 2015). "These include POLK, NIFK, SRGN, CAMP, CD109, and PLAC1 that are upregulated in several cancers resulting in metastasis and poor prognosis." (PMID 33110154, 2020). "Although CAMP, also known as LL-37, has been studied extensively, its antibacterial activities, its roles in the immune system and cancer, and its connection with sciatica have not been explored." (PMID 33535986, 2021).
bacterial infection (49 papers, 2011 to 2026). "Neutrophil extracellular traps (NETs) and the cathelicidin antimicrobial peptide LL-37 have been implicated both in defense against bacterial infections and in wound healing process." (PMID 30250474, 2018). "Vitamin D induced Camp gene up-regulated in VMB of PY model encodes cathelicidin antimicrobial peptide, which initiates the innate immune responses to bacterial infection, and can act as signaling molecule to regulate immune system function." (PMID 22563483, 2012). "Gene expression of defensin and cathelicidin antimicrobial peptide (CAMP) was performed to assess if fish skin treatment offers any benefit in protection against bacterial infections." (PMID 37888177, 2023). "Cathelicidin antimicrobial peptide (CAMP, LL-37) is an amphiphilic peptide with prominent roles in innate defense against bacterial infection." (PMID 35756995, 2022). "Furthermore, CAMP, a cationic antimicrobial peptide important for cellular defense against bacterial infection, was upregulated in BMSCs treated with the GH‐MCD hydrogels." (PMID 39840502, 2025). "Amongst the proteins identified during proteomic analysis that were decreased in CepEVs were DEFA3, LYZ, CAMP, LTF, and BPIFB1, all of which had strong associations with defense response to bacterium (GO: 0042742), as well as the immune response to bacterial infection." (PMID 41550953, 2025). "In BG_YPO category, lipoic acid metabolism and CAMP resistance were enriched, which suggested that the coenzyme with strong antioxidant and detoxifying properties and the capacity for protecting against bacterial infection were added." (PMID 39544673, 2024). "CAMP plays a critical role in innate immunity against invasive bacterial infections." (PMID 30971730, 2019). "Therefore, the up regulation of antimicrobial proteins in cluster 5 like CAMP and Lcn2 observed after IR could be related to protection against bacterial infection and modulation of oxidative stress." (PMID 30555831, 2018).
infectious disease (14 papers, 2008 to 2025). A disorder directly resulting from the presence and activity of a microbial, viral, or parasitic agent in humans. "Differential expression of CYP24A1 and CAMP may affect vitamin D status and susceptibility to infectious diseases, respectively." (PMID 23805323, 2013). "It is expected that the molecular regulatory mechanism of the CAMP gene during the occurrence of diseases, especially infectious diseases, will become a topic of significant further research." (PMID 32792959, 2020). "As an innate immune effector molecules, LL37 is a human cathelicidin antimicrobial peptide encoded by CAMP gene, plays an important role in the control of infectious diseases." (PMID 32265874, 2020). "Due to the important role that the CAMP protein plays in infectious diseases, tumors, and other diseases, it may be a target for the diagnosis and treatment of these diseases." (PMID 32792959, 2020). "Decreased CAMP expression in Africans may contribute to the infectious disease burden of South Africa; currently ranked globally with the third highest TB burden." (PMID 23805323, 2013).
cardiovascular disease (9 papers, 2014 to 2024). "Our divergent results in mice and human patients suggest a species-dependent CAMP regulation in cardiovascular diseases." (PMID 38474156, 2024). "Among these, CPA3, CAMP, and IL3RA have been found to exhibit strong connections with cardiovascular disorders." (PMID 38753730, 2024). "In contrast to these findings, no regulation of CAMP in CAD patients is observed, with its potential role as a biomarker in cardiovascular diseases thus remaining rather questionable." (PMID 38474156, 2024).
inflammation (5 papers, 2020 to 2026). Aberrant reaction of the microcirculation characterized by movement of fluid and leukocytes from the blood into extravascular tissues. "CAMP, therefore, might play a role as an adipokine in metaflammation and adipose inflammation." (PMID 37958808, 2023).
hematological malignancies (2 papers, 2016 to 2022). "With regard to pro-tumorigenic activities, PDE4 inhibitors were reported to inhibit proliferation, migration, and progression of several solid tumors as well as hematological malignancies probably via cAMP-PKA signaling." (PMID 27602951, 2016).
immune diseases (2 papers, 2014 to 2025). "Since sex hormones, especially estrogen, had immune-modulatory properties and contributed to sex-bias susceptibility to some immune diseases, the effects of estrogen on LTF, CAMP and DEFA4 were also explored in the present study." (PMID 24741625, 2014).
Neurological diseases (1 paper, 2024). "Neurological diseases in the brain are largely influenced by the AKT/CREB/BDNF signaling pathway, which is involved in protein kinase B/CAMP response element binding protein/brain-derived neurotrophic factor." (PMID 38946910, 2024).
CAMP also shares sentences with these, for which no sentence is quoted: ovarian cancer (22 papers); Autoimmunity (11); prostate carcinoma (11); colitis (10); gastric cancer (9); atopic dermatitis (7); inflammatory skin disease (7); keratitis (7); psoriatic arthritis (7); Crohn disease (6); Erythema (6); influenza (6); oral squamous cell carcinoma (6); type 1 diabetes (6); congenital neutropenia (5); E. coli infection (5); neutropenia (5); pancreatic cancer (5); staphylococcus aureus infection (5); ulcerative colitis (5); acute myeloid leukaemia (4); gastritis (4); lung disease (4); ovarian tumor (4); Papillon-Lefèvre syndrome (4); pneumococcal meningitis (4); pulmonary TB (4); urinary tract infection (4); acute coronary syndrome (3); acute leukemia (3).
A further 177 diseases each share a sentence with CAMP in 3 papers or fewer.